Y_RNA (Y RNA )
Gene: Miscellaneous RNA gene on chromosome 2 (43,620,878 to 43,620,984, reverse strand). Ensembl gene ENSG00000207411.
Homologues: Orthologues: chimpanzee Y_RNA (100% identical), macaque Y_RNA (93% identical). Paralogues in human: Y_RNA (80% identical), Y_RNA (79% identical), Y_RNA (78% identical), RNY1 (77% identical), RNY1P7 (77% identical), Y_RNA (77% identical), RNY1P14 (76% identical), Y_RNA (76% identical), RNY1P5 (75% identical), RNY1P9 (75% identical), Y_RNA (75% identical), Y_RNA (74% identical), and 85 more.